SMN2 (survival of motor neuron 2, centromeric)
Description:
The SMN complex catalyzes the assembly of small nuclear ribonucleoproteins (snRNPs), the building blocks of the spliceosome, and thereby plays an important role in the splicing of cellular pre-mRNAs. Most spliceosomal snRNPs contain a common set of Sm proteins SNRPB, SNRPD1, SNRPD2, SNRPD3, SNRPE, SNRPF and SNRPG that assemble in a heptameric protein ring on the Sm site of the small nuclear RNA to form the core snRNP (Sm core). In the cytosol, the Sm proteins SNRPD1, SNRPD2, SNRPE, SNRPF and SNRPG are trapped in an inactive 6S pICln-Sm complex by the chaperone CLNS1A that controls the assembly of the core snRNP. To assemble core snRNPs, the SMN complex accepts the trapped 5Sm proteins from CLNS1A forming an intermediate. Within the SMN complex, SMN1 acts as a structural backbone and together with GEMIN2 it gathers the Sm complex subunits. Binding of snRNA inside 5Sm ultimately triggers eviction of the SMN complex, thereby allowing binding of SNRPD3 and SNRPB to complete assembly of the core snRNP. Ensures the correct splicing of U12 intron-containing genes that may be important for normal motor and proprioceptive neurons development. Also required for resolving RNA-DNA hybrids created by RNA polymerase II, that form R-loop in transcription terminal regions, an important step in proper transcription termination. May also play a role in the metabolism of small nucleolar ribonucleoprotein (snoRNPs).
Synonyms: SMNC; BCD541; GEMIN1; TDRD16B; C-BCD541
Target class: Methyl-lysine/arginine binding protein; Reader; Epigenetic regulator; Tudor domain
Chemical probes: ML104, ML200, ML372
Gene: Protein-coding gene on chromosome 5 (70,049,635 to 70,078,522, forward strand). Ensembl gene ENSG00000205571.
Subcellular location: Nucleus, gem; Nucleus, Cajal body; Cytoplasm; Cytoplasmic granule; Perikaryon; Cell projection, neuron projection; Cell projection, axon; Cytoplasm, myofibril, sarcomere, Z line
Subcellular location (Human Protein Atlas): Cytosol; Nuclear bodies
Pathways (Reactome):
Disease: SARS-CoV-2 modulates host translation machinery
Metabolism of RNA: snRNP Assembly
Gene Ontology:
Molecular function: identical protein binding; protein binding; RNA binding
Biological process: DNA-templated transcription termination; spliceosomal complex assembly; spliceosomal snRNP assembly; axonogenesis; mRNA processing; RNA splicing, via transesterification reactions
Cellular component: Cajal body; cytoplasm; cytoplasmic ribonucleoprotein granule; cytosol; Gemini of Cajal bodies; neuron projection; nuclear body; nucleoplasm; nucleus; perikaryon; SMN complex; SMN-Sm protein complex; axon; Z disc
Homologues: Orthologues: chimpanzee SMN2 (100% identical), macaque SMN1 (93% identical), dog SMN (85% identical), mouse Smn1 (82% identical), rat Smn1 (75% identical), tropical clawed frog smn1 (54% identical), zebrafish smn1 (49% identical), Caenorhabditis elegans smn-1 (23% identical), Drosophila melanogaster Smn (20% identical). Paralogues in human: SMN1 (100% identical), SMNDC1 (19% identical).
Diseases named in the same sentence as SMN2 in open-access papers:
SMN2 is named in the same sentence as 62 diseases in open-access papers, as found by Europe PMC text mining. Sharing a sentence is not in itself a finding about the gene and the disease. The quoted sentences say what the papers report.
spinal muscular atrophy (310 papers, 2008 to 2026). A motor neuron disease that affect the muscles, and characterized by muscle weakness and atrophy resulting from progressive degeneration and irreversible loss of the anterior horn cells in the spinal cord (i.e., lower motor neurons) and the brain stem nuclei. "Spinal muscular atrophy (SMA) is another example where mutations in the SMN1/SMN2 genes reduce the assembly of U snRNPs, impairing splicing and motor neuron survival." (PMID 39940824, 2025). "Spinal muscular atrophy (SMA) is caused by homozygous loss of the SMN1 gene with SMN2 gene copy number correlating with disease severity." (PMID 39139818, 2024). "Suppression of a strong ISS motif with the intent to induce exon re-inclusion has been previously investigated as a therapeutic strategy in ApoER2, GAA and SMN2 genes, which underlie Alzheimer disease, Pompe disease and spinal muscular atrophy, respectively." (PMID 38182646, 2024). "The conversion from SMN2 to SMN1 which was found in 6 patients with spinal muscular atrophy (SMA) is causative for disease as a result of a synonymous variant that is introduced in the SMN1 gene." (PMID 37891200, 2023). "Given the need for clarity in practice, this review summarizes several clinically relevant variants in the SMN1 and SMN2 genes, including how they inform outcomes for spinal muscular atrophy carrier risk and disease prognosis." (PMID 36140824, 2022). "This is important because improving SMN2 exon 7 inclusion is a goal of therapeutic strategies to treat patients with spinal muscular atrophy, which is caused by defects in the SMN1 gene resulting in SMN protein deficiency." (PMID 36123433, 2022). "Mutations—point mutations and copy number changes—in the SMN1 and SMN2 genes cause a rare childhood disorder called spinal muscular atrophy (SMA) and SMN1 is one of the most-studied duplicated genes in the genome." (PMID 35680869, 2022). "For example, CRISPR-based editing was used to convert SMN2 to an SMN1-like gene in hiPSCs derived from patients with Spinal Muscular Atrophy (SMA) caused by homozygous SMN1 gene deletions." (PMID 36699015, 2022). "For example, when the goal is to promote the inclusion of a coding exon, such as the case with SMN2 exon 7 linked to spinal muscular atrophy (SMA), an ideal target must be a negative regulatory element, which is accessible and located within an intron." (PMID 34445083, 2021). "The presence of the SMN2 paralogue was successfully harnessed to treat spinal muscular atrophy: Because of a noncoding point mutation, the SMN2 mRNA splicing pattern typically lacks exon 7 and produces a truncated protein." (PMID 34882671, 2021). "A profound example of nearly unmappable CDS regions with high clinical relevance are the SMN1 and SMN2 genes, mutations in which cause spinal muscular atrophy (SMA) - a fatal neurological disorder with an early age of onset." (PMID 32029882, 2020). "Several model systems have shown hnRNP G to be a key modulator of alternative splicing in multiple genes implicated in neurogenerative disease including SMN2 in spinal muscular atrophy and microtubule-associated protein tau (MAPT) in FTLD." (PMID 32748079, 2020). "Spinal Muscular Atrophy results from loss-of-function mutations in SMN1 but correcting aberrant splicing of SMN2 offers hope of a cure." (PMID 31127278, 2019). "SMN1 and SMN2 are camouflaged by each other, where both genes are known to contribute to spinal muscular atrophy, and have been implicated in ALS." (PMID 31104630, 2019). "OSTF1 has also been demonstrated to interact with Survival of Motor Neuron 1 and 2 (SMN1 and SMN2 respectively), the loss of which leads to spinal muscular atrophy." (PMID 28936620, 2017). "Deletion of and/or mutations in SMN1 coupled with the inability of SMN2 to compensate for the loss of SMN1 leads to spinal muscular atrophy (SMA), a leading genetic disease of children and infants." (PMID 27111068, 2016).
spinal muscular atrophy (continued). "The inability of SMN2 to compensate for the loss of SMN1 results in spinal muscular atrophy (SMA), a debilitating childhood disease." (PMID 23861442, 2013). "Examples include SMN2 mutations, which induce motor neuron degeneration in spinal muscular atrophy, and mutations in the RNA-binding proteins TDP-43 and FUS, which induce amyotrophic lateral sclerosis." (PMID 23865419, 2013). "Here, we report a long-distance interaction (LDI) as a critical regulator of alternative splicing of Survival Motor Neuron 2 (SMN2) exon 7, skipping of which is linked to spinal muscular atrophy (SMA), a leading genetic disease of children and infants." (PMID 23861442, 2013). "The universal presence of a gene (SMN2) nearly identical to the mutated SMN1 gene responsible for Spinal Muscular Atrophy (SMA) has proved an enticing incentive to therapeutics development." (PMID 22558076, 2012). "The inability of SMN2 to compensate for the loss of SMN1 results in spinal muscular atrophy (SMA), a leading genetic cause of infant mortality." (PMID 23185376, 2012). "Copy number variants in the SMN1/SMN2 locus, which cause spinal muscular atrophy, may also lead to first trimester miscarriages as found in our study (PL-098D), however further investigation is required to establish this novel gene-disease association." (PMID 41256177, 2025). "In the case of the Spinal Muscular Atrophy Registry, in addition to genetic validation (type of disease-causing variants/deletion, SMN2 copy number), it is important to confirm the type of SMA depending on the maximum motor level reached—without DMTs—and the age of onset of symptoms." (PMID 38373977, 2024). "Spinal muscular atrophy (SMA) is an autosomal recessive motor neuron disease that is caused by deletions or mutations in the Survival Motor Neuron 1 (SMN1) gene but retention of its nearly perfect orthologue SMN2." (PMID 35741345, 2022). "The oral, selective SMN2-splicing modifier risdiplam obtained European approval in March 2021 for the treatment of patients ≥ 2 months old with a clinical diagnosis of 5q-associated spinal muscular atrophy (SMA) 1/2/3 or with 1–4 SMN2 gene copies." (PMID 35854272, 2022). "In consequence, splicing defects on SMN1 and SMN2—and the emergence of a neurodegenerative disorder such as spinal muscular atrophy—might be associated with a subset of hnRNP proteins." (PMID 30487551, 2018). "Spinal muscular atrophy (SMA) is a motor neuron disease caused by homozygous mutations in the survival motor neuron 1 (SMN1) gene that are partially compensated by the paralogous SMN2 gene." (PMID 29895323, 2018). "For example, a silent variation in SMN2 was hypothesized to create a binding site of the repressor hnRNPA1 which reduced the inclusion of exon 7 of SMN2 and caused spinal muscular atrophy." (PMID 25985083, 2015). "However, no similar AS alterations were detected in Huh-7 cells treated with four more potent pHi-affecting amiloride analogues, including EIPA, which we previously showed to modulate the pathogenic SMN2 transcript in cells of spinal muscular atrophy patients." (PMID 21694768, 2011). "5q spinal muscular atrophy (SMA) is an autosomal-recessive motor neuron disease caused by the bi-allelic loss of function of the survival of motor neuron 1 (SMN1) gene on chromosome 5q13 with at least one functional copy of the paralogous survival of motor neuron 2 (SMN2) gene." (PMID 39596191, 2024). "SMA (spinal muscular atrophy) is an autosomal recessive disease that is characterized by different mutations such as a C->T within the exon 7, causing an exclusion that drives the production of a truncated form of the survival of the motor neuron 2 (SMN2) protein." (PMID 35806476, 2022).
spinal muscular atrophy (continued). "For example, in order to compensate for the loss of the functional SMN1 gene, the therapy of Spinal Muscular Atrophy intends to increase the expression of SMN2 gene by enhancing the inclusion of a normally skipped exon 7, which is necessary to produce a functional transcript of SMN2 gene." (PMID 26400733, 2015). "Background/Objectives: Nusinersen is a synthetic antisense RNA oligonucleotide employed in the management of spinal muscular atrophy, a rare neuromuscular disorder, by modulating the alternative splicing of the survival motor neuron 2 (SMN2) gene." (PMID 41754920, 2026). "Background and Objectives: Spinal muscular atrophy (SMA) is a progressive, autosomal recessive, rare neuromuscular disorder caused by a genetic defect in the SMN1 gene, where the SMN2 gene cannot sufficiently compensate." (PMID 40282862, 2025). "Risdiplam is an orally administered small molecule that modifies the mRNA splicing of SMN2 for the treatment of spinal muscular atrophy (SMA)." (PMID 41007035, 2025). "The second example is nusinersen, a 2′MOE-PS SSO that facilitates SMN2 exon 7 inclusion and is an approved treatment for spinal muscular atrophy." (PMID 39926316, 2025). "In the study, an SSO (brand name Nusinersen), specifically targeted SREs, was used to prevent the skipping of SMN2 (survival of motor neuron 2) exon 7, increasing the total amount of intact SMN2, and greatly relieved spinal muscular atrophy." (PMID 39877462, 2025). "Branaplam was originally developed as a splice enhancer of exon 7 in the SMN2 gene, which increases full-length SMN2 protein and compensates for loss of SMN1 function in spinal muscular atrophy." (PMID 41311869, 2025). "Spinraza, an ASO approved for spinal muscular atrophy, alters the splicing of survival motor neuron 2 (SMN2) pre-mRNA to increase the production of functional SMN protein, significantly improving patient outcomes." (PMID 41211454, 2025). "Branaplam is a small molecule RNA splicing modulator promoting changes in alternative splicing of the survival of motor neuron 2 (SMN2) mRNA1 and underwent clinical investigation in spinal muscular atrophy (SMA) (NCT02268552)." (PMID 40343270, 2025). "For example, the SSO Nusinersen that treats Spinal Muscular Atrophy targets the intron downstream of exon 7 in the SMN2 pre-mRNA, to block binding of the splicing repressor hnRNPA1." (PMID 38664594, 2024). "We looked through published literature to create a set of considerations for treatment in patients with Spinal Muscular Atrophy including age, type, SMN2 copies, and any familial considerations." (PMID 38671712, 2024). "Deletion or disruption of SMN1 is associated with spinal muscular atrophy (SMA) and its paralogue, SMN2, is the target of one of the most successful ASO-mediated gene therapies." (PMID 39372794, 2024). "Spinal muscular atrophy (SMA) patients benefit from pre-mRNA splicing modifiers targeting the SMN2 gene, which aims to increase functional SMN production." (PMID 39707482, 2024). "Prevention of SMN2 exon 7 skipping has implications for the treatment of spinal muscular atrophy (SMA)." (PMID 38214229, 2024). "Spinal muscular atrophy, a common muscular disorder, most commonly caused by a copy number change in the SMN1 gene and modified by the copy numbers of SMN2, is also missed by WES." (PMID 38167091, 2024). "Risdiplam is a once-daily oral, survival of motor neuron 2 (SMN2) splicing modifier approved for the treatment of spinal muscular atrophy (SMA)." (PMID 38733387, 2024). "A genotype–phenotype correlation suggests that SMN2 is a potent disease modifier in spinal muscular atrophy (SMA)." (PMID 39844848, 2024). "Our principal objective is to describe the sociodemographic characteristics and evaluate the association between the number of SMN2 copies and SMA type in patients from the Colombian Foundation for Spinal Muscular Atrophy (FAMECOL) database." (PMID 39518541, 2024).
spinal muscular atrophy (continued). "Spinal muscular atrophy (SMA) is a consequence of homozygous loss of SMN1 expression and insufficient expression of functional SMN from the SMN2 gene." (PMID 38727321, 2024). "Spinal muscular atrophy (SMA) is a progressive neuromuscular disorder caused by mutations in SMN1, with disease severity influenced by the number of SMN2 copies." (PMID 39720178, 2024). "Nusinersen, which targets the splicing of former pseudogene SMN2, is a highly successful treatment for spinal muscular atrophy." (PMID 38924406, 2024). "Type III SMA (Kugelberg-Welander disease) is typical among children older than 18 months, and their copy number of the SMN2 gene is typically four." (PMID 38920997, 2024). "For instance, nusinersen, an ASO approved for spinal muscular atrophy (SMA), enhances exon inclusion in the SMN2 gene to compensate for the loss of function in the SMN1 gene." (PMID 39795966, 2024). "The antisense oligonucleotide nusinursen targets pre-mRNA splicing of the SMN2 gene, giving clinically meaningful benefits in the childhood ataxia, spinal muscular atrophy (SMA)." (PMID 39263555, 2024). "In a recent study, the MS assay was also applied in CNV detection of SMN1 and SMN2 genes for spinal muscular atrophy genetic testing, showing highly concordant results with MLPA." (PMID 38274092, 2023). "The survival motor neuron 2 (SMN2) gene is a modifier gene of spinal muscular atrophy (SMA); a lower SMN2 copy number is associated with increased disease severity." (PMID 38136980, 2023). "Validated targets can modulate mRNA splicing or modify the expression of factors implicated in human disease, such as inducing SMN2 expression in spinal muscular atrophy." (PMID 38033386, 2023). "PE was also used to precisely delete the intronic splicing silencer-N1 (ISS-N1) within survival motor neuron 2 (SMN2) to rescue full-length SMN expression in human iPSCs derived from spinal muscular atrophy (SMA) patients." (PMID 37626665, 2023). "Studies propose that individuals with a lower copy number of SMN2 and a more severe phenotype of spinal muscular atrophy are more likely to have structural heart malformations." (PMID 37303748, 2023). "For example, an 18-mer ASO targeting an intronic splicing silencer increased the inclusion of exon 7 of SMN2 in a humanized mouse model of spinal muscular atrophy." (PMID 36893203, 2023). "Risdiplam is an oral, survival of motor neuron 2 (SMN2) pre-mRNA splicing modifier approved for the treatment of spinal muscular atrophy (SMA)." (PMID 36735057, 2023). "For example, Spinraza, an FDA-approved treatment that corrects the splicing of SMN2 for spinal muscular atrophy, must be administered by direct injection into the spinal column." (PMID 37635865, 2023). "For instance, the FDA-approved Nusinersen targeting SMN2 to treat spinal muscular atrophy has shown remarkable efficacy in the clinic." (PMID 37012334, 2023). "The survival motor neuron 2 (SMN2) gene is a recognized modifier gene of spinal muscular atrophy (SMA)." (PMID 38136980, 2023). "Here, we report final results for 14 children with two copies of SMN2, expected to develop spinal muscular atrophy (SMA) type 1." (PMID 35715566, 2022). "Most children with biallelic SMN1 deletions and three SMN2 copies develop spinal muscular atrophy (SMA) type 2." (PMID 35715567, 2022). "There is an article entitled “Spinal Muscular Atrophy—Is Newborn Screening Too Late for Children with Two SMN2 Copies?”." (PMID 36421785, 2022). "Spinraza is an FDA-approved drug that can modulate splicing of the SMN2 gene to generate full-length SMN2 protein and thus improve the motor function of spinal muscular atrophy patients." (PMID 36271053, 2022). "In spinal muscular atrophy, a stem-loop RNA structure overlaps with the 5′ splicing site of exon 7 of SMN2 and interference with the structure formation is a therapeutic target against the spinal muscular atrophy molecular phenotype." (PMID 35765654, 2022).